CAT (catalase)
Diseases named in the same sentence as CAT in open-access papers (continued):
Sharing a sentence is not in itself a finding about the gene and the disease.
perinatal asphyxia (1 paper, 2021). A disorder caused by a lack of blood flow or gas exchange to or from the fetus in the period immediately before, during, or after the birth process. "We also showed that the oxidative microenvironment resulting from the reduced antioxidant activity of SOD, CAT, GPx, and GSH levels and increased GSSG levels is still present at PD15, confirming previous findings in other perinatal asphyxia models." (PMID 34040692, 2021).
Peripheral edema (1 paper, 2019). An abnormal accumulation of interstitial fluid in the soft tissues of the limbs. "CAT rs1001179 A allele was significantly associated with peripheral edema (OR = 0.32; 95%CI = 0.15–0.68; p = 0.003)." (PMID 30813952, 2019).
Peritoneal Fibrosis (1 paper, 2010). Disorder characterized by a wide range of structural changes in PERITONEUM, resulting from fibrogenic or inflammatory processes. "Taken together with previous reports that acatalasemic mice are susceptible to oxidative renal fibrosis and peritoneal fibrosis, our data also support that catalase plays a crucial role in protection from fibrotic disorders." (PMID 21190578, 2010).
phyllodes tumor (1 paper, 2024). A benign, borderline, or malignant fibroepithelial neoplasm arising from the breast and rarely the prostate gland. "Noticeable differences in the metabolism of phyllodes tumors are demonstrated by a decrease in the level of chlorides, CAT, and urea, and an increase in the content of DC and lactate." (PMID 39452912, 2024).
plaque psoriasis (1 paper, 2020). "High levels of plasma and red blood cell malondialdehyde (MDA) resulting from decreased activity of CAT and GPx were reported as markers of plaque psoriasis exacerbation." (PMID 31998446, 2020). "In SWS of psoriatic patients, we observed considerably higher concentration of Px and CAT, and in erythrocytes of patients with plaque psoriasis, the concentration of GPx and CAT was significantly higher compared to that in the controls." (PMID 31998446, 2020). "The activity of all antioxidant enzymes in NWS of patients with plaque psoriasis was significantly higher than that in the controls (Px, p = 0.0051; CAT, p ≤ 0.001; SOD, p = 0.004)." (PMID 31998446, 2020). "The value of AUC for CAT activity in erythrocytes of patients with plaque psoriasis was 0.85." (PMID 31998446, 2020). "The concentration of Px, CAT, and SOD was significantly higher in NWS of patients with plaque psoriasis vs. healthy subjects." (PMID 31998446, 2020).
porphyria (1 paper, 2016). Porphyria is a group of diseases in which substances called porphyrins build up, negatively affecting the skin or nervous system. "However, and independently from the H2O2 levels produced in circulating blood cells, this toxic compound cannot be properly detoxified by catalase activity, a haem-containing enzyme which tends to be defective in porphyria patients." (PMID 27788171, 2016). "In addition to the higher ROS production presented by porphyria patients, the accumulation of porphyrins could also affect the functionality of antioxidant enzymes such as catalase, thus impairing the ROS detoxifying capacity." (PMID 27788171, 2016).
primary effusion lymphoma (1 paper, 2022). A large B-cell lymphoma located in the body cavities, characterized by pleural, peritoneal, and pericardial fluid lymphomatous effusions and that is always associated with human herpes virus-8 (HHV-8).
primary sclerosing cholangitis (1 paper, 2020). "Catalase is one of the autoantigens in primary sclerosing cholangitis, suggesting that a redox unbalance caused by catalase antibodies could contribute to its pathogenesis." (PMID 32435643, 2020).
progeria (1 paper, 2022). "Further, peroxisomal OS is particularly crucial in the cell lifespan and survival ability and CAT plays an utmost role in this sense, so that CAT inactivation may lead, due to an impaired mitochondria-peroxisome cross-talk, to a condition of premature aging, also known as progeria phenotype." (PMID 35883714, 2022).
pyelonephritis (1 paper, 2017). An inflammatory process affecting the kidney. "In the pyelonephritis, SOD, CAT activity, and lipid peroxidation levels were abnormal and these were refunded to nearly usual and overturned by TQ treatment in the pyelonephritis." (PMID 28983249, 2017).
renovascular hypertension (1 paper, 2024). High blood pressure secondary to renal artery stenosis. "Training has been shown to increase the activity of the superoxide dismutase and catalase in the heart and kidney in a model of renovascular hypertension." (PMID 38653584, 2024).
RSV bronchiolitis (1 paper, 2020). "Infants and young children carrying the genotypes of the catalase SNP rs1001179 with the CT/TT allele were found to have significantly less severe RSV bronchiolitis in our study population, suggesting a protective effect on disease severity." (PMID 31947722, 2020). "Though our results suggest a newly described association of catalase rs1001179 with decreased RSV bronchiolitis severity, co-morbidities and other predisposing genetic factors are likely to play an important role in patients with the CT/TT genotype who present with different illness severities." (PMID 31947722, 2020). "One SNP in the promoter region of the catalase gene, rs1001179, which is associated with higher enzyme expression, was significantly underrepresented (p = 0.01, OR 0.38) among patients with moderate to severe RSV bronchiolitis, suggesting a protective effect against disease severity." (PMID 31947722, 2020). "Of the evaluated SNPs that is found in the promoter region of catalase gene, thus resulting in higher enzyme expression, was found to be remarkably underrepresented among patients with moderate to severe RSV bronchiolitis compared to patients with milder forms of the disease." (PMID 31947722, 2020).
sexual dysfunction (1 paper, 2019). Disturbances in sexual desire and the psychophysiologic changes that characterize the sexual response cycle and cause marked distress and interpersonal difficulty.
skin aging (1 paper, 2021). The gradual irreversible changes in structure of skin that occur as a result of the passage of time.. "As TF FOXM1, which was modified by phosphorylation, was activated, the target gene CAT was upregulated to inhibit ROS accumulation in both young-adult and middle-aged skin aging." (PMID 34073305, 2021).
sleep-disordered breathing (1 paper, 2022). "Several factors have been identified (e.g., sex, polymorphisms in the TASK2/KCNK5, NOTCH4 and CAT genes and pre-term birth) to predict individual vulnerabilities to hypoxia-related sleep-disordered breathing." (PMID 36582343, 2022).
spinal cord injuries (1 paper, 2021). "A low level of catalase has been reported in spinal cord injuries, and catalase has been used to monitor treatment response." (PMID 37551326, 2021).
spinocerebellar ataxia 1 (1 paper, 2019). "Like CAA interruptions in HTT, CAT interruptions of the ATXN1 CAG repeat in four spinocerebellar ataxia 1 subjects supported better tracking of age at onset with the uninterrupted CAG repeat size, but, because CAT specifies histidine, this was interpreted as an effect of polyglutamine length." (PMID 31398342, 2019).
Spinocerebellar ataxia type 3 (1 paper, 2017). "Additionally, in patients and cell models for spinocerebellar ataxia type 3, it has been shown that oxidative stress could be associated with a significant alteration of SOD and CAT enzymatic activities." (PMID 28659860, 2017).
ST elevated myocardial infarction (1 paper, 2021). "The study aimed to assess levels of ischemia modified albumin (IMA), malondialdehyde acid (MDA), superoxide dismutase (SOD), and catalase in individuals diagnosed with ST elevated myocardial infarction (STEMI) and non-STEMI." (PMID 34177373, 2021).
T-cell lymphoma (1 paper, 2023). "Moreover, indices such as reduced glutathione (GSH), superoxide dismutase (SOD), and catalase (CAT) exhibited amplified activities in DLA cells and murine serum post AgNPs-CGA-BSA treatment, positing a prospective therapeutic avenue for T-cell lymphoma." (PMID 37781708, 2023).
temporal lobe epilepsy (1 paper, 2018). A localization-related (focal) form of epilepsy characterized by recurrent seizures that arise from foci within the temporal lobe, most commonly from its mesial aspect. "Previous studies have found increased activities of SOD, CAT, markers of lipid peroxidation and decreased activities of glutathione peroxidase (GPx) in pharmacoresistant temporal lobe epilepsy (TLE) patients." (PMID 29890748, 2018).
testicular degeneration (1 paper, 2021). "Cisplatin also, suppresses the activity of antioxidant enzymes (GSH, SOD and CAT) and increases free radical levels (hydrogen peroxide and lipid peroxide) in the testes, all these processes are factors which are prerequisite to testicular degeneration." (PMID 34647003, 2021).
Thiamine deficiency (1 paper, 2021). Thiamine deficiency is a condition that occurs due to not enough thiamine (vitamin B1). "On the other hand, thiamine deficiency induces changes in oxidative metabolism and promotes oxidative stress through diminished antioxidants activity of CAT, SOD, and GSH and thus disables their ability to neutralize free radicals which finally leads to cell injury." (PMID 34630136, 2021).
thrombophilia (1 paper, 2020). A condition characterized by an abnormally high level of thrombi. "Similarly, CAT activity was lower in inherited thrombophilias during the first two trimesters." (PMID 32555583, 2020).
tinea (1 paper, 2021). "canis strains from humans with tinea corporis (n = 10) and from animals presenting (n = 64) or not (n = 26) skin lesions was employed to evaluate phospholipase (Pz), hemolytic (Hz), lipase (Lz), catalase (Ca), and thermotolerance (GI) activities." (PMID 33809233, 2021).
transitional cell carcinoma (1 paper, 2018). A malignant neoplasm arising from the transitional epithelium, usually affecting the urinary bladder, ureter, or renal pelvis. "With respect to superficial transitional cell carcinomas, catalase and MnSOD expression was significantly lower in invasive transitional cell carcinomas, thus appearing to be associated with progression of BC." (PMID 30042310, 2018).
tularemia (1 paper, 2010). Tularemia is an infection caused by the bacterium Francisella tularensis. "The immunoreactive proteins included several proteins that were observed to be increased in expression during the later stages of murine tularemia (Acetyl CoA caboxylase, Chitinase family 18 protein, Peroxidase/Catalase and hypothetical protein FTT1303c)." (PMID 20368994, 2010).
Turner syndrome (1 paper, 2014). Turner syndrome is a chromosomal disorder associated with the complete or partial absence of an X chromosome. "CAT activity increased in M and Turner's syndrome patients (P = 0.05) in comparison to C subjects." (PMID 25101153, 2014). "There was also an increase in CAT activity in M and Turner' syndrome." (PMID 25101153, 2014). "Our results showed that CAT increased in the patients with M and Turner's syndrome." (PMID 25101153, 2014).
type 1 diabetic nephropathy (1 paper, 2021). "Under high glucose (HG), peripheral blood mononuclear cells showed decreased catalase (CAT), CuZn superoxide dismutase (SOD), and glutathione peroxidase (GPx) mRNA expression in patients with type 1 diabetic nephropathy." (PMID 33562389, 2021).
unstable angina pectoris (1 paper, 2023). "Antioxidant enzymes SOD and CAT were significantly increased in patients with unstable angina pectoris compared to their healthy controls in coronary arterial blood samples, while the significant elevation of SOD in the experimental group was also noticed in peripheral venous blood samples." (PMID 37511912, 2023).
Wilms tumor (1 paper, 2024). An embryonal neoplasm characterized by the presence of epithelial, mesenchymal, and blastema components. "The elevated superoxide dismutase activity, along with the reduced catalase activity observed in Wilms’ tumors, could lead to an overproduction of hydrogen peroxide." (PMID 39334568, 2024).
tumor (688 papers, 1956 to 2026). "Genetic variants of antioxidant enzymes, namely in SOD2, GPX1, and CAT, were already associated with the development of various neoplasms and treatment efficacy." (PMID 40565143, 2025). "During tumor development, tumor cells often reduce cell death and DNA damage caused by high levels of ROS by inducing the expression of CAT." (PMID 37313408, 2023). "Studies have previously shown downregulation of catalase in some cancers and upregulation of catalase in other cancers is associated with tumor progression and metastasis." (PMID 37311396, 2023). "CAT polymorphisms can affect the expression of CAT mRNA in tumor tissues, and according to TCGA data analysis, the OS and PFS of LUAD patients with high CAT expression is significantly longer (p = 0.020, p = 0.048 respectively)." (PMID 36969849, 2023). "Superoxide anions inhibit catalase, so tumor cells express membrane-associated superoxide dismutase (SOD) to maintain catalase activity." (PMID 38069213, 2023). "The second is through the indirect killing effect associated with the catalase (CAT) or superoxide dismutase (SOD) activity of nanozymes by altering the common hypoxia of the tumor microenvironment (TME)." (PMID 37376150, 2023). "The reason behind the control of HOCl signaling at later stages of tumor progression can be attributed to the membrane-associated catalase on the tumor cells." (PMID 35794980, 2022). "A similar mechanism was observed in vitro in cancer cells, where translocation of Catalase to the outside of the cell membranes was associated with cellular transformation and tumor progression." (PMID 35522719, 2022). "Resistance to apoptosis via triggering intercellular ROS signaling via membrane-associated catalase owing to decomposing hydrogen peroxide, peroxynitrite, and oxidizing NO appears to be one of the characteristics of tumor growth." (PMID 36176404, 2022). "These basic features of oncogenesis are the resistance of tumor cells to intercellular ROS signaling through membrane-associated catalase expression." (PMID 36176404, 2022). "Singlet oxygen produced in this way can inhibit tumor cell membrane-associated catalase and SOD, resulting in the flow of CAP-derived ROS/RNS into tumor cells." (PMID 35646968, 2022). "The exposure to CAP or PAM initially inactivates only a small percentage of protective membrane-associated catalase molecules in the tumour cells." (PMID 33801451, 2021). "The essential resistance principle of tumor cells, according to Deichman’s concept, has been determined as membrane-associated catalase." (PMID 34679719, 2021). "Xu and Pan have shown that an Agrobacterium strain deficient in catalase activity was highly attenuated in the ability to cause tumours on plants compared with the wild type." (PMID 33765920, 2021). "Approach B utilized the specific chemical biology of tumor cells that reactivate intercellular NO/peroxynitrite or HOCl signaling after inhibition of membrane-associated catalase." (PMID 34679719, 2021). "Approach A focused on apoptosis induction in tumor cells after inhibition of membrane-associated catalase and addition of excess exogenous H2O2." (PMID 34679719, 2021). "Singlet oxygen has the potential to inactivate membrane-associated catalase and to trigger the generation of secondary singlet oxygen by targeted tumor cells." (PMID 34679719, 2021). "Inactivation of membrane-associated catalase of tumor cells reactivates extracellular NOX1-driven ROS/RNS signaling through the NO/peroxynitrite or the HOCl signaling pathway." (PMID 34679719, 2021). "Tumour cells are protected against intercellular apoptosis by inducing signalling with increased expression of membrane-associated enzymes catalase and superoxide dismutases." (PMID 33801451, 2021). "Approach B utilized the reactivation of intercellular NO/peroxynitrite or HOCl signaling after inhibition of tumor cell membrane-associated catalase by 3-AT." (PMID 34679719, 2021).